RABIF (RAB interacting factor)
Description:
Guanine-nucleotide-releasing protein that acts on members of the SEC4/YPT1/RAB subfamily. Stimulates GDP release from both YPT1, RAB3A and RAB10, but is less active on these proteins than on the SEC4 protein. Might play a general role in vesicular transport.
Synonyms: MSS4; RASGRF3; RASGFR3
Tractability: PROTAC: its protein half-life has been measured.
Gene: Protein-coding gene on chromosome 1 (202,878,282 to 202,889,149, reverse strand). Ensembl gene ENSG00000183155.
Subcellular location (Human Protein Atlas): Cytokinetic bridge; Microtubules
Gene Ontology:
Molecular function: protein binding; zinc ion binding; guanyl-nucleotide exchange factor activity
Biological process: membrane fusion; post-Golgi vesicle-mediated transport; small GTPase-mediated signal transduction
Cellular component: cytosol; membrane
Genetic constraint (gnomAD): Loss-of-function variants: 13 observed, 11.98 expected, observed/expected ratio (o/e) 1.08, 90% interval 0.7 to 1.69. The upper end of that interval is the gene's LOEUF score, 1.69, which puts it in group 6 of 6, group 1 being the genes least tolerant of losing a copy. Missense variants: 153 observed, 161.12 expected, observed/expected ratio (o/e) 0.95, 90% interval 0.83 to 1.09. Synonymous variants: 70 observed, 65.72 expected, observed/expected ratio (o/e) 1.07, 90% interval 0.88 to 1.3.
Homologues: Orthologues: chimpanzee RABIF (99% identical), macaque RABIF (99% identical), rabbit RABIF (97% identical), dog RABIF (95% identical), mouse Rabif (93% identical), rat LOC120100841 (92% identical), rat Rabif (92% identical), pig RABIF (89% identical), guinea pig RABIF (69% identical), tropical clawed frog rabif (67% identical), zebrafish rabif (66% identical), Drosophila melanogaster strat (37% identical), and 1 more.
Diseases named in the same sentence as RABIF in open-access papers:
RABIF is named in the same sentence as 7 diseases in open-access papers, as found by Europe PMC text mining. Sharing a sentence is not in itself a finding about the gene and the disease. The quoted sentences say what the papers report.
breast carcinoma (2 papers, 2021 to 2024). "The results revealed that shorter relapse-free survival (p < 0.001) and overall survival (p < 0.001) were significantly associated with breast cancer patients with higher RABIF expression than those with lower RABIF expression." (PMID 34685504, 2021). "RABIF was once to be identified as a new biomarker candidate of breast cancer development by a bioinformatics tool named PINCAGE (probabilistic integration of cancer genomics data for perturbed gene)." (PMID 34685504, 2021). "Both miR-491-5p and RABIF were found to possess clinical impact on survival in breast cancer and/or TNBC patients." (PMID 34685504, 2021). "Our study revealed that miR-491-5p and RABIF are influential prognostic biomarkers in breast cancer and TNBC." (PMID 34685504, 2021). "Our data first indicated that RABIF, as a direct target of miR-491-5p, is a poor prognostic factor in breast cancer and TNBC." (PMID 34685504, 2021). "High expression of RABIF was found to be correlated with poor clinical outcomes of breast cancer and TNBC patients." (PMID 34685504, 2021). "We determined the survival rates of breast cancer and TNBC patients according to RABIF expression levels by applying the Kaplan–Meier plotter." (PMID 34685504, 2021). "Given the lack of clarity regarding the role of RABIF in breast cancer, particularly TNBC, we further explored the functional roles of RABIF in TNBC." (PMID 34685504, 2021). "Although miR-491-5p was also found to target JMJD2B and ZNF-703 to act as a tumor suppressor in breast cancer no investigations to pinpoint that RABIF is a direct target of miR-491-5p in breast cancer especially in TNBC in the past." (PMID 34685504, 2021). "Interestingly, RABIF was found to be structurally similar to translationally controlled tumor protein (TCTP) and TCTP was depicted as prognostic factor and a crucial regulator in CSC compartment in breast cancer." (PMID 34685504, 2021).
pancreatic cancer (1 paper, 2021). "Human RABIF gene was found to be located at chromosome 1q32.1 and high level of RABIF mRNA expression was once reported in pancreatic cancer tissues." (PMID 34685504, 2021).
triple-negative breast carcinoma (1 paper, 2022). An invasive breast carcinoma which is negative for expression of estrogen receptor (ER), progesterone receptor (PR), and human epidermal growth factor receptor 2 (HER2). "Increased RABIF expression in breast and triple negative breast cancer patients is related to poorer outcome and considered a potential bioprognostic marker." (PMID 36059641, 2022). "MiR-491-5p was reported to directly targeting RABIF to downregulate cell invasion, metastasis, and drug resistance in triple negative breast cancer." (PMID 36059641, 2022).
cancer (4 papers, 2018 to 2024). A tumor composed of atypical neoplastic, often pleomorphic cells that invade other tissues. "For many genes, their function in cancer is still unknown while some others have already been implicated in cancer such as: RABIF, KLHL12, ADIPOR1, CYBR5R1 and PRELP." (PMID 29844869, 2018). "Nevertheless, the actual character of RABIF in regulating cancer development and metastasis has remained obscure." (PMID 34685504, 2021). "We are also the first to report that RABIF is the direct target of miR-491-5p to regulate cancer stemness, drug resistance, cell invasion and pulmonary metastasis via MMP signaling in TNBC." (PMID 34685504, 2021). "Since RABIF acts as a GEF and GEF has been previously reported to be involved in cancer cell migration, invasion, and metastasis, we then choose RABIF as the most potential target of miR-491-5p for further investigation." (PMID 34685504, 2021). "We revealed that miR-491-5p also directly targeted RABIF and downregulated RABIF-mediated TNBC cancer stemness, drug resistance, cell invasion, and pulmonary metastasis via matrix metalloproteinase (MMP)-2 and MMP-9 signaling." (PMID 34685504, 2021). "MiR-491-5p was first reported to directly target Rab interacting factor (RABIF) to downregulate RABIF-mediated TNBC cancer stemness, drug resistance, cell invasion, and pulmonary metastasis via matrix metalloproteinase (MMP) signaling." (PMID 34685504, 2021). "We are also the first to elucidate that RABIF functions as an oncogene to promote cancer stemness, drug resistance, cell invasion and pulmonary metastasis which can be reverted by miR-491-5p mediated inhibition in TNBC." (PMID 34685504, 2021). "Targeting the novel FOCAD/miR-491-5p/RABIF/MMP signaling pathway could be a promising strategy to overcome cancer stemness and drug resistance in TNBC to improve treatment efficacy." (PMID 34685504, 2021). "Furthermore, RABIF (RAB interacting factor) was mutated in GTPase Sec4 and was speculated to be involved in cancer cell progression, invasion, and metastasis." (PMID 37181805, 2023).
tumor (2 papers, 2021 to 2022). "In conclusion, our study shed light on the novel tumor suppressor role of FOCAD/miR-491-5p to target RABIF/MMP signaling in TNBC." (PMID 34685504, 2021). "In the present study, we unveiled the novel tumor suppressor role of FOCAD/miR-491-5p via targeting RABIF/MMP signaling in TNBC for the first time." (PMID 34685504, 2021). "RABIF is highly expressed in a range of immune cells and malignant cells, and we speculate that it may affect tumor progression and prognosis by regulating malignant cells and proliferating T cells." (PMID 36059641, 2022).
RABIF also shares sentences with these, for which no sentence is quoted: gastric cancer (1 paper); melanoma (1).